BDNF (brain derived neurotrophic factor)
Diseases named in the same sentence as BDNF in open-access papers (continued):
Sharing a sentence is not in itself a finding about the gene and the disease.
sarcoidosis (3 papers, 2010 to 2025). Sarcoidosis is a multisystemic disorder of unknown cause characterized by the formation of immune granulomas in involved organs. "We confirm and extend these results by showing positive NGF, BDNF and NT-3 immunostaining in alveolar macrophages present within the lung parenchyma of sarcoidosis patients." (PMID 21059230, 2010). "This study shows that not only the NGF protein, but also NT-3 protein, was elevated in BALF from sarcoidosis patients as compared to healthy subjects, while BDNF protein levels were undetectable in both healthy subjects and sarcoidosis patients." (PMID 21059230, 2010). "To elucidate the cellular targets for NGF, BDNF and NT-3 within the airways in sarcoidosis, we studied the presence of the corresponding neurotrophin receptors, TrkA, TrkB and TrkC, in lung biopsies." (PMID 21059230, 2010). "BALF concentrations of NGF and neurotrophin-3 (NT-3) were significantly increased, and immunoreactivity against NGF, BDNF, NT-3, and tyrosine protein kinase receptors (TrkA, TrkB, and TrkC) in granulomas was found in patients with sarcoidosis using immunohistochemical analysis." (PMID 40361957, 2025). "Despite the lack of detectable levels of BDNF in BALF, we could detect both BDNF and its receptor in the granulomas and airway cells in sarcoidosis by immunohistochemistry in a similar fashion as for NGF and NT-3." (PMID 21059230, 2010). "The sarcoidosis patients showed significantly enhanced NT-3 and NGF levels in BALF, whereas BDNF was undetectable in both patients and controls." (PMID 21059230, 2010). "In addition, Ricci and co-workers have demonstrated that immune cells, such as alveolar macrophages and T-lymphocytes, retrieved from BAL from sarcoidosis patients, express NGF, NT-3 and BDNF to a larger degree than BAL cells from healthy subjects." (PMID 21059230, 2010). "However, less is known about levels of BDNF and NT-3, and moreover, knowledge in the cellular sources of neurotrophins and the distribution of the corresponding neurotrophin receptors in airway tissue in sarcoidosis is lacking." (PMID 21059230, 2010).
sensorineural hearing loss (3 papers, 2020 to 2023). "Therefore, in the present study we investigated the effects of recombinant human BDNF on HCs and SCs of the organ of Corti in a model of kanamycin-induced severe sensorineural hearing loss." (PMID 35053747, 2021). "Indeed, studies have demonstrated that exogenous administration of BDNF may be considered a promising tool for diverse types of neurodegenerative disorders including brain disease, olfactory impairment, and sensorineural hearing loss." (PMID 37109038, 2023). "Notably, recombinant human BDNF administration was effective in preventing SGC death following hair cell degeneration in vivo, and therefore represents a promising therapeutic strategy for the treatment of sensorineural hearing loss." (PMID 35053747, 2021).
small cell lung carcinoma (3 papers, 2016 to 2025). Small cell lung cancer (SCLC) is a highly aggressive malignant neoplasm, accounting for 10-15% of lung cancer cases, characterized byrapid growth, and early metastasis. "Interestingly, recent evidence showed that serum BDNF level was down-regulated in the patients with advanced small cell lung cancer." (PMID 36417428, 2022).
spinocerebellar ataxia type 1 (3 papers, 2018 to 2024). Spinocerebellar ataxia type 1 (SCA1) is a subtype of type I autosomal dominant cerebellar ataxia (ADCA type I) characterized by dysarthria, writing difficulties, limb ataxia, and commonly nystagmus and saccadic abnormalities. "Similarly, altered expression levels of BDNF have been observed in murine animal models of spinocerebellar ataxia type 1 (SCA1), which is a hNDD resulting from a mutation in the ATXN1 gene, causing progressive motor deficits." (PMID 39200370, 2024). "Post-mortem studies of patients with spinocerebellar ataxia type 6 (SCA6) show reduced expression of BDNF which was also revealed in a SCA6 mouse model, as well as a spinocerebellar ataxia type 1 (SCA1) mouse model." (PMID 37251644, 2023).
steatosis (3 papers, 2019 to 2025). Increased lipid within the cytoplasm of cells. "Most recently, BDNF has also been linked to a host of beneficial effects at systemic level, including decreased adiposity, improved glucose tolerance and reduced steatosis." (PMID 31188781, 2019). "Compared with nonvagotomized cirrhotic controls, vagotomized mice exhibit reduced levels of liver inflammation but increased levels of steatosis, increased brain-derived neurotrophic factor(BDNF) in the prefrontal cortex, and reduced glial cell activation." (PMID 40321299, 2025). "Hepatic vagal innervation affects the gut microbial composition, hepatic inflammation and steatosis, and cortical inflammation and BDNF expression and could be a critical modulator of the gut-liver-brain axis with consequences for HE development." (PMID 34248683, 2021).
Strabismus (3 papers, 2016 to 2020). A misalignment of the eyes so that the visual axes deviate from bifoveal fixation. "For example, 3 months of sustained release of brain derived neurotrophic factor (BDNF) in infant monkey EOM did not produce a strabismus, although it did result in significant alterations in myofiber types within the treated lateral rectus muscles." (PMID 30142211, 2018).
sudden infant death syndrome (3 papers, 2013 to 2015). Unexpected death in infancy which remains unexplained following autopsy, review of the medical history, and investigation of the death circumstances and death scene. "In victims of sudden infant death syndrome the KF nucleus shows clear signs of developmental immaturity and low levels of BDNF immunostaining." (PMID 26441556, 2015). "The KFN showed clear signs of developmental immaturity, prevalently associated to BDNF altered expression, in high percentages of sudden intrauterine unexplained death syndrome (SIUDS) and sudden infant death syndrome (SIDS) victims." (PMID 25237300, 2014). "Neuroprotective functions of the BDNF/TrkB axis may be reduced in the respiration nuclei in sudden infant death syndrome (SIDS) cases." (PMID 23670594, 2013).
Tension-type headache (3 papers, 2012 to 2022). A type of headache that last hours with continuous pain of mild or moderate intensity, bilateral location, a pressing/tightening (non-pulsating) quality and that is not aggravated by routine physical activity such as walking or climbing stairs. "BDNF values were also greater in the patients with tension-type headaches than in the control group." (PMID 36360388, 2022). "Another study also revealed higher levels of BDNF in migraine attacks compared to headache-free period and tension-type headaches." (PMID 34991456, 2022).
tetanus (3 papers, 2011 to 2021). A serious infectious disorder that follows wound contamination by the Gram-positive bacterium Clostridium tetani. "At the late stage of L-LTP (around 3 hour after tetanus), the BDNF-treated slices exhibited a much higher level of PKMζ compared with the one in the presence of anisomycin (161.6±20.5%, p<0.05)." (PMID 21747912, 2011). "Previous studies indicate that L-LTP can be further divided into the BDNF-dependent form which can be induced by theta burst stimulation (12 TBS) or a perfusion of cAMP analogs such as forskolin, and the BDNF-independent form which is triggered by the classic 4 sets of tetanus (4×tetani)." (PMID 21747912, 2011). "Moreover, there is a critical window for BDNF to rescue L-LTP impairment — no later than 10 minutes after tetanus." (PMID 21747912, 2011). "Unlike the classic, tetanus-induced L-LTP, the cAMP or 12TBS induced L-LTP requires an increase in local concentration of dendritic proteins but not nucleus activity, and is dependent on BDNF." (PMID 21747912, 2011).
Thrombocytopenia (3 papers, 2014 to 2022). A reduction in the number of circulating thrombocytes. "We postulate a priori that thrombocytopenia will be accompanied with BDNF and serotonin disorders that may impact the immune response as well viral control." (PMID 26491607, 2014).
Thrombocytosis (3 papers, 2017 to 2024). Increased numbers of platelets in the peripheral blood. "This can relate to thrombocytosis mechanism and utilization of BDNF after chronic, intensive, or long-term exercise." (PMID 38785805, 2024). "There are two interesting parallels between BDNF and platelet responses to exercise that suggest a primary role for thrombocytosis in BDNF elevation." (PMID 29056915, 2017). "This substantial BDNF response is associated with an intensity-dependent increase in circulating platelets indicative of thrombocytosis that we interpret as being a major source of exercise-induced BDNF in a forearm handgrip model." (PMID 29056915, 2017). "A closer look at the mechanism of thrombocytosis supports the potential for forearm handgrip exercise as a modality to achieve increases in serum BDNF." (PMID 29056915, 2017). "Our small muscle mass exercise protocols were designed based on the rationale that elevated sympathetic nervous activity was a required effect of exercise in order to induce thrombocytosis and thereby achieve serum BDNF elevation." (PMID 29056915, 2017). "This is because of the need for sufficient magnitude and duration of peripheral stimuli like shear stress or deoxygenation for endothelial or brain BDNF production and release, and sympathetic splenic vasoconstriction for thrombocytosis." (PMID 29056915, 2017). "Given that ~99% of circulating BDNF is platelet-bound, this thrombocytosis could account for a large part of the robust serum BDNF increase following acute exercise, even if only 30–40% of this BDNF is releasable." (PMID 29056915, 2017). "However, based on our findings it would appear that constriction of the spleen and the subsequent thrombocytosis is an important mechanism for elevating BDNF during exercise and forearm exercise provides ample stimulus for this." (PMID 29056915, 2017). "As such, it is plausible that performing small muscle mass exercise, such as, forearm handgrip exercise, could stimulate thrombocytosis and consequently achieve significant elevations in serum BDNF." (PMID 29056915, 2017). "Given that nearly 99% of blood-borne BDNF is platelet-bound, the addition of splenic platelets to the blood via thrombocytosis could account for a majority of the increased BDNF observed in response to exercise." (PMID 29056915, 2017). "Therefore, an exercise modality that evokes sufficient sympathetic outflow could stimulate exercise-induced thrombocytosis and subsequently increase circulating BDNF." (PMID 29056915, 2017). "We hypothesized that maximal effort exercise (ME) would significantly elevate serum BDNF and platelet levels compared to rest and compared to submaximal effort exercise (SE), as ME would result in greater sympathetic activation, and therefore thrombocytosis, compared to SE." (PMID 29056915, 2017). "Thus, we believe our work is the first to demonstrate that stimulation of thrombocytosis independent of muscle mass activation is an important consideration for an exercise modality's efficacy in elevating circulating BDNF." (PMID 29056915, 2017).
ulcerative colitis (3 papers, 2022 to 2025). An inflammatory bowel disease involving the mucosal surface of the large intestine and rectum. "Exosomal miR-29b of gut origin might impair heart function by suppressing brain-derived neurotrophic factor in patients with ulcerative colitis." (PMID 35274002, 2022).
Acidosis (2 papers, 2019 to 2021). Abnormal acid accumulation or depletion of base. "Acidosis, which is caused mainly by tumor cells and osteoclasts, activates the channels (TRPV1, ASICS3) and stimulates stromal cells to produce and release not only growth factors (e.g., NGF, brain-derived neurotrophic factor (BDNF)) but also pro-inflammatory mediators (e.g., IL1β, IL6, IL15, CCL5)." (PMID 31801267, 2019).
acute leukemia (2 papers, 2016 to 2021). A clonal (malignant) hematopoietic disorder with an acute onset, affecting the bone marrow and the peripheral blood. "However, it should be noted that BDNF and TrkB upregulation are associated with tumor cell survival in a number of solid cancers and in acute leukemias." (PMID 34695155, 2021).
Age-Related Hearing Loss (2 papers, 2021 to 2023). "Notably, a strongly modulation of BDNF expression has also been found in animal models of age-related hearing loss (ARHL)." (PMID 37109038, 2023). "Rüttiger and colleagues observed a significant reduction of BDNF levels, both at the RNA and protein level, in an animal model of presbycusis." (PMID 37109038, 2023).
albinism (2 papers, 2016). A congenital disorder characterized by partial or complete absence of melanin pigment in the eyes, hair, or skin. "Further work is needed to clarify the role that the pattern of BDNF expression and localization plays in EOM structure and function in the EOM of both subjects with idiopathic INS and those with INS and albinism." (PMID 27092717, 2016). "Alterations of BDNF may be a precipitating factor in the subjects with INS and albinism and in idiopathic INS." (PMID 27092717, 2016). "In contrast, the EOMs examined from the subjects with idiopathic INS and INS and albinism were largely negative for BDNF expression." (PMID 27092717, 2016). "In some of the specimens from subjects with idiopathic INS, small numbers of BDNF-positive myofibers could be seen (arrow), but these were extremely rare in the specimens from the subjects with INS and albinism." (PMID 27092717, 2016). "In the subjects with INS and albinism, these differences included smaller NMJ compared to control EOM, greater numbers of NMJ on fast myofibers expressing the immature γAChR, a higher percentage of and larger slow myofibers in these muscles, and the absence of BDNF-positive myofibers." (PMID 27092717, 2016).
alcohol withdrawal syndrome (2 papers, 2024). "Previous studies showed that BDNF played a significant role in the processes of alcohol withdrawal syndrome, and FGF21 is related to AUD." (PMID 38721616, 2024).
amenorrhea (2 papers, 2016 to 2024). The absence of menses in a woman who has achieved reproductive age. "At rest, eumenorrheic females showed higher values of BDNF in comparison to those experiencing amenorrhea." (PMID 39333320, 2024). "As CSH in transmen results in amenorrhea and therefore ovarian arrest, as well as atrophy of the endometrium, a decrease in BDNF would be the logical consequence." (PMID 26753091, 2016). "That sex steroids do play a role in peripheral BDNF regulation in natal females is supported by the fact that women with amenorrhea as well as postmenopausal women have decreased BDNF levels and hormone replacement therapy results in restoration up to levels seen in fertile women." (PMID 26753091, 2016).
asthenospermia (2 papers, 2021 to 2024). "Therefore, alterations in BDNF may be associated with an impaired capacity of sperm to defend against oxidative stress, contributing to asthenospermia and related disorders." (PMID 38886667, 2024).
Blindness (2 papers, 2017 to 2018). Blindness is the condition of lacking visual perception defined as a profound reduction in visual perception. "In summary, HDACi and a BDNF mimetic are sufficient to rescue retinal cell death and visual function in a vertebrate model of inherited blindness." (PMID 28900183, 2017). "In summary, characterisation of the mechanisms by which histone deacetylase inhibitors (HDACi) rescue visual impairment uncovered BDNF-TrkB signalling as necessary and sufficient to restore visual function in a model of inherited blindness." (PMID 28900183, 2017). "Here, we demonstrate in a vertebrate model of inherited blindness that HDAC inhibitors and BDNF mimetics are sufficient to significantly improve cone-photoreceptor mediated visual function via a BDNF mediated signalling dependent mechanism of action." (PMID 28900183, 2017).
bowel obstruction (2 papers, 2020). "BDNF mRNA and protein expression are also increased in the smooth muscle cells of a rat model of bowel obstruction (Lin, Fu, Radhakrishnan, Huang, & Shi, 2017)." (PMID 31976585, 2020).
breast tumors (2 papers, 2014 to 2019). "Using data of The Cancer Genome Atlas (TCGA), a prevalent loss of BDNF gene expression in breast tumors when compared to normal breast tissues could be confirmed." (PMID 25036590, 2014). "Autocrine BDNF/TrkB activation has been shown to promote metastatic traits in primary breast tumors." (PMID 30796353, 2019). "Next, we confirmed in a further independent data set of 2.878 breast tumors (KMPLOT) the known prognostic impact of BDNF expression on recurrence-free survival (RFS)." (PMID 25036590, 2014). "A direct coherence of the identified BDNF/SFRP1 expression axis is further supported by the significant correlation of BDNF and SFRP1 protein expression in primary breast tumors." (PMID 25036590, 2014).
Cachexia (2 papers, 2015 to 2025). Severe weight loss, wasting of muscle, loss of appetite, and general debility related to a chronic disease. "Changes in BDNF expression or its signaling may have implications for muscle function and atrophy in cachexia." (PMID 40869331, 2025). "Although there is no direct evidence linking BDNF to cachexia, it is speculated that this molecule could modulate the pathogenesis of muscle wasting in cachexia, as it is known to affect muscle maintenance and regeneration." (PMID 40869331, 2025). "It was hypothesized that cytokines as IL-1, IL-6, IFN-γ, TNF-α, brain-derived neurotrophic factor, MIC-1 may be involved in the cachexia process, in the imbalance which favors catabolism over anabolism, and in the neurologic and neuropsychiatric manifestations of the disease." (PMID 26337554, 2015).
celiac disease (2 papers, 2023 to 2025). An autoimmune genetic disorder with an unknown pattern of inheritance that primarily affects the digestive tract. "The same speculation may be applied in celiac disease, where adult patients have lower serum BDNF concentrations, whereas children with celiac disease have increased BDNF concentrations in comparison with healthy controls." (PMID 37548699, 2023).
central precocious puberty (2 papers, 2025). "Neurotrophins—particularly BDNF—have been implicated in the pathophysiology of central precocious puberty (CPP), potentially contributing to premature maturation and activation of hypothalamic GnRH neurons." (PMID 41614834, 2025). "Serum brain-derived neurotrophic factor (BDNF) levels were measured in girls with central precocious puberty (CPP) and matched controls." (PMID 41244054, 2025).
cerebral small vessel disease (2 papers, 2022 to 2023). Cerebral small vessel disease is the term currently used to pathological processes that affect the brain parenchymal circulation (arterioles, capillaries, and veins). "Furthermore, blood biomarkers of neurodegeneration including plasma Aβ-40, Aβ-42, total tau, phosphorylated tau 181 (p-tau181), and BDNF levels and image markers of cerebral small vessel disease were measured." (PMID 35572134, 2022).
Chronic colitis (2 papers, 2014 to 2021). A chronic inflammatory disease of the large intestine (colon, cecum and rectum). "Our results indicate that chronic colitis upregulates IL-1β augmenting certain cardiac miRNAs, particularly miR-155, which leads to suppression of BDNF corresponding to impaired heart function." (PMID 34543287, 2021). "In total, these findings support BDNF’s role as a mediator of chronic colitis-induced cardiac dysfunction." (PMID 34543287, 2021). "Our results are in agreement with previous observations that hippocampal BDNF mRNA expression is lowered in chronic colitis induced by Trichuris muris." (PMID 25414650, 2014). "It is unclear, however, if chronic colitis suppresses BDNF by upregulating certain miRNAs." (PMID 34543287, 2021).
chronic lymphocytic leukemia (2 papers, 2020 to 2025). "In chronic lymphocytic leukemia, elevated BDNF levels were related to a favorable outcome." (PMID 40427122, 2025).